Y_RNA (Y RNA )
Gene: Miscellaneous RNA gene on chromosome X (9,874,601 to 9,874,701, reverse strand). Ensembl gene ENSG00000206844.
Homologues: Orthologues: chimpanzee Y_RNA (99% identical). Paralogues in human: RNY3 (87% identical), Y_RNA (87% identical), RNY3P1 (86% identical), Y_RNA (86% identical), Y_RNA (85% identical), Y_RNA (84% identical), RNY3P11 (83% identical), RNY3P5 (83% identical), Y_RNA (83% identical), RNY3P14 (82% identical), Y_RNA (82% identical), RNY3P16 (81% identical), and 93 more.